CD79A (CD79a molecule)
Diseases named in the same sentence as CD79A in open-access papers (continued):
Sharing a sentence is not in itself a finding about the gene and the disease.
tumor (continued). "We also studied the cellular interactions between tumor cells of NLPHL pattern A and THRLBCL on the one hand and CD8+ and PD1+ T cells in 3D thick tissue slices double-stained with CD79a on the other hand." (PMID 35173297, 2022). "Immunohistochemically, tumor cells had an intact B-cell phenotype with the expression of CD20, CD79a and PAX5." (PMID 36606194, 2022). "The tumor cells, i.e., the lymphocyte-predominant (LP) cells, have functional B-cell receptors and express B-cell antigens like CD20, CD79a, PAX5, and OCT23,4." (PMID 35173297, 2022). "The CD79A/CD40 co-stimulatory structural domain confers enhanced proliferative capacity of CAR-T cells and increased anti-tumor effects in mouse models." (PMID 35741714, 2022). "These TLSs were stained with CD38, CD138, and CD79a to distinguish GCs (which are CD20− but co-express CD38, CD138, and cytosolic CD79a) from naïve and memory B cells (which are CD38−CD138− but express membranous CD79a) and CD138+ tumor or stromal cells." (PMID 34553849, 2021). "The mRNA expression data prompted us to stain tumour sections to validate immune-related expression, by which we chose seven immunophenotypical markers [CD45, CD4, CD8, FOXP3, CD79A, Kappa/Lambda (K/L) and SLAMF7] to study both T cell and B cell expression." (PMID 32195184, 2020). "The Lgals9-based network by Cytoscape showed extensive and complex correlation between Lgals9 and other molecules in tumor-immune microenvironment, including CD4, CD19, CD79A, CIS, IL2RG, FCGR2C, and FASLG." (PMID 33082168, 2020). "In terms of pathological diagnosis, the immunophenotype analysis showed that the stromal lymphocytes were positive for CD20, CD79a, and BCL-2, while the tumor cells were positive for BCL-10, NF-kB, p65 and PAX-5." (PMID 33585230, 2020). "We next generated cell lines in which the CD79a gene was ablated with the CRISPR/Cas9 technique and found that depleting CD79a (CD79a-KO) suppressed tumor cell proliferation." (PMID 31942184, 2020). "The staining showed that the cells in tumour stroma were α‐SMA positive fibroblasts, CD79a positive B lymphocytes and CD3 positive T lymphocytes." (PMID 30734495, 2019). "Tumor cells show expression of pan-B cell markers (CD19, CD20, and CD79a) and lack the expression of CD5, CD10 (a marker of germinal center B cells)." (PMID 29740389, 2018). "CHL tumor cells were positive for PAX5 (10/12, 83.3%), CD30 (12/12, 100%), CD15 (9/12, 75.0%), CD20 (4/12, 33.3%) and CD79a (2/9, 22.2%)." (PMID 28566711, 2017). "Immunohistochemical staining showed that tumor cells were positive for CD20, CD79a, and BCL2 expression." (PMID 28122582, 2017). "The tumour exhibited a CD20+, CD79a+, CD 10+, immunophenotype, Bcl-2 focal positivity, Ki-67 >90% positivity, whereas other markers were negative including CD3, CD45RO, CD15, CD30, ALK and EMA." (PMID 26990772, 2016). "Cells within the encapsulated mediastinal tumor stained strongly positive (+++) for CD45 and CD79a, PAX5, and CD20, and positive (+) for BCL-2 and MUM1." (PMID 26715530, 2015). "Tumor histopathology was graded for necrosis, inflammation, and infiltration of T, B, and dendritic cells (CD3-CD4+ and CD8+, CD79a, CD18) pre-treatment and on days 8 and 29 post-treatment." (PMID 26091536, 2015). "Based on immunohistochemical staining, the phenotype of the tumor cells was CD3+, CD43+, CD56+, TIA-1+, CD30+, CD4-, CD5-, CD7-, CD8-, CD20- and CD79a-." (PMID 26126576, 2015). "We next evaluated tissue from tumor bearing mice (tumor mass, spleen, intestine and kidney) by immunohistochemical analysis for the expression of CD3, CD5, CD19, CD20, CD23, CD45, CD79a, Ki-67, cyclin D1, and Pax5." (PMID 24722054, 2014). "In the present case, the patient’s tumor cells exhibited positive labeling for the B-cell antigens CD20, CD79a, CD10 and BCL-6, as well as a high proliferation index, which was detected using Ki-67 staining and was found to be 80%." (PMID 25013515, 2014).
tumor (continued). "The tumor cells expressed CD20 (7 of 7), CD79a (6 of 6), BCL2 (5 of 7), BCL6 (4 of 7) and MUM1 (5 of 7)." (PMID 23915571, 2013). "Immunohistochemically, tumor cells showed CD3+, CD45RO+, CD5-, CD7-, CD4-, CD8-, CD10-, CD20-, CD30-, CD79a-, CD138-, CD56-, granzyme B-, TIA-1+ and ALK-." (PMID 22931631, 2012). "Immunohistochemically, the tumor cells were cytokeratin -, vimentin +, CD3+, CD45RO+, CD5-, CD7-, CD4-, CD8-, CD10-, CD20-, CD30-, CD79a-, CD138-, CD56-, granzyme B-, TIA-1 cytotoxic granule-associated RNA binding protein (TIA-1) + and ALK-." (PMID 22931631, 2012). "The skin biopsy was performed, but this time the tumor was composed of large, polymorphous population of lymphocytes with CD20 and CD79a positive on immunohistochemical staining." (PMID 22260632, 2012). "The results revealed that PTCL-S1 highly expresses CD30 and CD3, and is negative for CD79a, which is concordant with the patient tumour and PDX tissue." (PMID 40715645, 2025). "B cell markers (CD20, CD79a, and PAX-5) were positive in the tumor cells." (PMID 40933576, 2025). "However, the remaining two cases displayed diffuse positivity for CD20 but variable CD79a expression (variable intensity in one case and partial expression in the other), and also expressed MUM1 in the majority of tumour cells." (PMID 41047873, 2025). "A biopsy of the retroperitoneal tumor showed proliferation of small, atypical lymphoid cells with high nuclear-to-cytoplasm ratio, positive for CD10, CD19, CD79a, BCL-2, BCL-6, and c-MYC by immunohistochemistry." (PMID 41142614, 2025). "Tumor cells typically express B-cell antigens (CD19, CD20, and CD79a) and monoclonal IgM." (PMID 39221368, 2024). "Additionally, we compared the distribution of B cells (based on CD79A and CD79B expressions) between the control and tumor groups." (PMID 38386050, 2024). "Indeed, MCLs express the neoplasm markers of mature B cells, namely CD19, CD20, CD22, CD79-A, and Cyclin D1." (PMID 38828423, 2024). "However, from a prognostic perspective, CD5, SLCO1B1, and CD79A have been demonstrated to have protective value in various tumors, whereas ETV5, FZD7, SNX7, and SLC1A7 are involved in tumor progression." (PMID 37680641, 2023). "The tumor cells in PBDLBCL are positive for CD45, CD20, CD79a, and PAX5 (B‐cell markers)." (PMID 40625579, 2023). "Lymphoid follicles were a combination of CD3 and CD79a positive cells, but composition did not appear to change between treated and untreated tumor samples at the sampled time point (not shown)." (PMID 37196996, 2023). "The panels were designed to identify cytotoxic T cells (CD8+ GZMB+ CD3+), myeloid-derived suppressor cells (MDSCs) (CD11b+ CD33+ HLA-DR-negative) and B cells (CD20+ CD79a+), as well as a panel with CD3 and FOS to confirm the high expression of FOS in the tumour cells." (PMID 36982943, 2023). "CD79A/CD40 co-stimulated CAR-T cells also had superior anti-tumor activity and proliferative activity compared to CD28 or 4-1BB co-stimulated CAR-T cells in mice inoculated with Raji tumor cells." (PMID 35053463, 2022). "Following tumor sectioning immunohistochemistry for CD3, CD79a, and IBA-1 was performed." (PMID 35848421, 2022). "In our initial analysis, rare non-tumor cells clustered separately from tumor cells, and their identity was further validated by the expression of well-known stromal markers including Vim, Ptprc, Trpm5, Pecam1, Mgp, Cd79a, Itgam, Adgre1, Cd3g, and Marco." (PMID 33821796, 2021). "CD20, CD79a, PAX5 which were markers of B lymphocyte was strong in almost 90% of tumor nuclei." (PMID 33585230, 2020). "Our findings, therefore, raise the possibility that ETS1 amplifies the tumor-promoting effects of these mutants by increasing their expression and, indeed, ETS1 gains are common in the ABC-DLBCL cluster 5 characterized by MYD88 and CD79A/B." (PMID 32679859, 2020).
tumor (continued). "Moreover, immunohistochemical analysis revealed that tumor cells were positive for CD20, CD79a, PAX5, CD21, and CD23 and expression of CD3, CD5, and CD8 were observed in reactive T lymphocytes surrounding tumor cells." (PMID 33585230, 2020). "We then assessed whether cell sociology of tumor cells with CD3+ CD8-, CD79a+, and CD3+ CD8+ immune cell neighbors was able to improve recurrence classification of individual patients as compared to the density of these three cell types." (PMID 30651131, 2019). "Thus, tumor cells often express pan B-cell markers (cluster of differentiation 19 [CD19], CD29, CD79a) and in 90% of cases express BCL-6 and MUM1, whereas plasma cell-associated proteins such as CD38 and CD138 are usually absent." (PMID 30446015, 2018). "Immunohistochemical analysis revealed that the tumor cells were CD79a positive and CD3 negative, which is consistent with the profile of the lymphoid cells in the femoral arterial thrombi." (PMID 30373554, 2018). "In detail, high numbers of CD20+ and CD79a+ cells in the infiltrative margin but not in the tumor area and in the liver periphery showed this positive effect on patient outcome after tumor surgery." (PMID 29050338, 2017). "In B-LBL, tumour cells are virtually always positive for B cell markers CD19, CD79a and CD22." (PMID 26416427, 2015). "The bone marrow aspirate and biopsy revealed normocellular haematopoiesis, and no tumour cells were detected based on negative immunohistochemical analysis (CD79a, CD20, and CD3)." (PMID 24511310, 2014). "Further staining in other areas of the tumor revealed solid areas of CD20+CD79a+PAX-5+CD43+ positive cells that lacked T-cell antigens and EBER RNA." (PMID 23738160, 2013). "The tumor cells were diffusely positive for CD79a, Bob1, EMA, CD138, MUM-1, and IgA and negative for CD5, IgM and IgG." (PMID 23425357, 2013). "Furthermore, CLL tumor cells which are unresponsive to anti-IgM, can respond to anti-CD79a treatment, indicating a deficit in signal transmission from the BCR to CD79a/b." (PMID 23072591, 2012). "Histopathologically, the submucosal tumor uniformly showed a vague, nodular pattern composed of a regular proliferation of CD3-CD10-CD20+CD79a+bcl2+ small lymphoid cells with islands of abortive CD10+Ki67+ germinal centers, without evidence of marginal zone formation or lymphoepithelial lesions." (PMID 19829839, 2009). "A mouse model confirmed that CD79A allows bone marrow-derived suppressor cells to maintain their immature state, enhances the ability to suppress T-cell proliferation, stimulates their migration, and induces the secretion of protumor cytokines such as IL-6 and CCL22, thereby promoting tumor growth." (PMID 37344840, 2023). "In addition, some tumor cells showed a well-circumscribed cytoplasm of variable size, making them look lymphoblastic-like; however, the tumor cells were mature B cells, labelled positive in the immunohistochemical staining of CD20 and CD79a." (PMID 37872367, 2023). "In concurrence with NanoString analysis of our own tumor samples, these included IFN-γ signaling genes STAT1, CXCL10, and IDO1; antigen presentation molecules HLA-DQA1 and HLA-DRB1; important T cell molecules GZMB and IL7R; and B cell–related molecules CD79A and CXCL13." (PMID 35132960, 2022). "We hypothesized that CXCL13 expressed in T cells and CD79A and IGLL5 expressed in B cells could affect the expression of LHFPL2 gene through the CD45 signaling pathway, acting on macrophages, thus jointly playing a role in tumor regulation." (PMID 34900411, 2021). "Since they were mononuclear cells present in tumor microenvironment, mainly in stroma, we conducted immunofluorescence staining using markers for mast cells (mast cell tryptase), macrophages (CD68), plasma cells (CD38), T- and B- lymphocytes (CD3, CD20 and CD79a) and neutrophils (NE)." (PMID 29543850, 2018). "The tumor cells were positive for CD79a and negative for CD3." (PMID 30373554, 2018).
tumor (continued). "In addition, no staining was observed by tumour-associated macrophages or other inflammatory cells, such as CD3+ T-cells or CD79a+ B-lymphocytes." (PMID 20969772, 2010). "In order to find out whether a particular subtype of lymphocytes contained the S100A4, serial sections of some tumour specimens were immunocytochemically stained with antibodies to S100A4, and also with antibodies to CD3 and CD79a antigens for T and B lymphocytes, respectively." (PMID 11875708, 2002). "However, due to the overly high cell density of the tumour nest and the limited IMC resolution, some adjacent tumour cells and infiltrated immune cells were recognised as epithelial–immune dual feature cells, such as Clusters 4 (KRT5+, KRT19+, CD20+ and CD79A+) and 14 (KRT5+, KRT19+ and LYZ+)." (PMID 37349991, 2023). "The abundance of inflammatory cells that express CD79A protein, or high levels of miR-125b-5p or miR-99a-5p in the resected tumor tissues was not different in patients with short versus long PFS, although a single section may not represent the overall extent of expression across an entire tumor." (PMID 34484811, 2019). "Immunohistochemical staining showed strong expression of CD20, CD79a, and PAX5 in tumor cells, but CD3, CD56, and TIA1 were not expressed in tumor cells." (PMID 41291370, 2025). "These cells tested positive for CD10, CD79a, PAX-5, BCL-2, BCL-6 (10-20%), and c-MYC, but most tumor cells were negative for CD20 on immunohistochemistry." (PMID 41142614, 2025). "Tumour cells expressed vimentin, S-100 and NSE and were negative to CD3, CD20, CD79a, MHC II, MUM1, desmin, c-Kit, pancytokeratin and α-SMA." (PMID 40045318, 2025). "The tumor cells were negative expression of CgA, CD56, CK5/6, CK20, Myogenin, MyoD1, Desmin, CEA, S100, CK8/18, CDX2, CD20, CD5, CD3, CD79a, LCA and HMB45." (PMID 38877473, 2024). "The tumor cells expressed the B cell markers CD20, CD79a, and PAX-5 but were negative for CD3, ER, and PR." (PMID 37884941, 2023). "Assessment of tumor samples for lymphocyte infiltration (CD3, CD4, CD8, and CD79a) revealed no distinguishable differences between treated and untreated samples." (PMID 35834467, 2022). "Immunohistochemistry staining shows monoclonal cytoplasmic defected α-heavy chains that lack light chains and the expression of CD20 positivity on tumor cells, CD138, CD79a, and IgA positivity on plasma cells, and no expressions of CD5 and CD10 on tumor cells." (PMID 35621691, 2022). "Tumor cells are usually negative for CD45 and the pan-B-cell markers CD19 and CD20, and positive for CD38, CD79a, and CD138." (PMID 34930458, 2021). "The tumor cells are positive for CD45, CD30, CD15, MUMi, and Ki-67 (80%) and negative for CD20, PAX-5, CD79a, CD3, CD5, CD10, BCL6, BCL2, EMA, ALK-1, and CD138." (PMID 34900354, 2021). "Immunohistochemically, the tumor cells were negative for CD20, CD79a, CD3, CD5, c-kit, CD34, and TdT and positive for myeloperoxidase, CD33, CD68, and CD163." (PMID 34970464, 2021). "For the diagnosis of BPDCN, the tumor should be negative for other myelomonocytic, NK, T, and B lineage markers (CD34, CD8, MPO, lysozyme, PAX5, CD20, CD79a, EBV, and T-cell receptor protein)." (PMID 31752482, 2020). "Immunohistochemical analysis showed that the tumor cells on the surface and the necrotic interior of the thrombi were positive for CD20 and CD79a but negative for CD3, which is characteristic of B cells." (PMID 30373554, 2018). "Tumor cells are positive for CD20 and CD79a or abnormal expression of CD43, and negative for CD5, CD10 and Cyclin D1." (PMID 29489937, 2018). "In our case, tumor cells were positive for BOB1, MUM1, and EBER-ISH, partially positive for CD79a, and negative for CD20, CD56, CD138, CD3, CD5, AE1/AE3, and HHV8, which was most consistent with plasmablastic lymphoma." (PMID 27034868, 2016). "Immunohistochemically, tumor cells are characterized by CD30, ALK, CD5, TIA-1, Granzyme B, EMA positive staining, and CD2, CD3, CD7, CD4, CD8, CD20, CD79a negative staining." (PMID 27612448, 2016).
tumor (continued). "Immunohistochemically, the tumor cells were strong positive for CD56, CD3ε, TIA1, and weak positive for LMP1, and negative for CD5, CD8, CD20, CD79a, CgA, Syn, SCLC, CK, EMA, CD99, CD10, TdT, PAX-5, and BCL-6." (PMID 23958352, 2013). "The tumor cells in the present case were positive for CK, CAM5.2, SMA, CK19, CR and CD34, while the markers for bcl-2, PLAP, CD117, S-100, CD20, CD79a, CD45RO, CD15, CD30 were negative." (PMID 23946800, 2013). "By immunochemical staining of cytospins from the ascitic fluid of tumor cells were negative for CD45, as well as for CD19 and CD79A." (PMID 23880011, 2013). "The immunohistochemistry staining showed that the tumor cells were diffusely positive for S-100, CD1a, langerin and CD68, but negative for CD3, CD5, CD20, CD21, CD30, CD38, CD56, CD79a, ALK, HMB-45, Melan-A, pan-cytokeratin and MPO." (PMID 23388086, 2013). "Tumor cells were negative for keratin AE1/AE3, keratin 7, keratin 20, epithelial membrane antigen (EMA), CD79a, and immunoglobulin kappa light chain." (PMID 23133774, 2012). "The tumor cells are almost always negative for CD20 and CD79a but are always positive for CD138 and CD38, consistent with a postgerminal center phenotype." (PMID 22474449, 2012). "The tumor cells were CD45+, CD30+, CD38+, HHV-8 LANA-1+; but were negative for CD3-, CD20-, CD19-, and CD79a- and EBV RNA+ on in situ hybridization." (PMID 21320326, 2011). "In most of the other tumours, except BC 12, staining showed invasive lymphocyte populations to be mainly of T-cell origin (CD3+/CD79a−) (not given)." (PMID 12838311, 2003). "IHC of the harvested tumour after 4 generations revealed similar characteristics to the original patient tumour, i.e. positive for CD3, CD30 and negative for CD79a This indicates that the xenograft can propagate and retain the characteristics of the original tumour." (PMID 40715645, 2025). "Therefore, we would like to explore the spatial relationship between CD79A+CD24-PANCK+-BCSCs subpopulation and CD8+ T cells with FOXP3+ or not to reveal the influence of CD79A+CD24-PANCK+-BCSCs subpopulation on CD8+T cells and tumor microenvironment." (PMID 38066053, 2023). "A routine immunohistochemistry antibody panel revealed that the tumor cells were negative for B-cell and T-cell markers (i.e., CD3, CD19, CD20, CD38, CD45RO, CD79a, CD138, and Pax-5), but were positive for CD30 and MUM-1, not defining the lineage of tumor cells." (PMID 28143608, 2017). "The tumor showed the proliferation of large lymphoid cells with centroblastic morphology, which were positive for CD138, CD38, CD56 and MUM-1, and negative for CD20, CD79a, BCL-6 and HHV8." (PMID 26543559, 2015). "Tumor cells stained negative for CD10, CD20, CD79a, CD34, CD56, CD117, TdT, Desmin, and EMA." (PMID 22497840, 2012). "Tumor cells were negative for S100 protein, kappa light chain, CD3, CD20, CD79a, and keratin KL1." (PMID 23133774, 2012).